MPO (myeloperoxidase)
Diseases named in the same sentence as MPO in open-access papers (continued):
Sharing a sentence is not in itself a finding about the gene and the disease.
COVID-19 (continued). "Higher levels of NETs are found by testing the levels of myeloperoxidase (MPO)/DNA complexes in the plasma of COVID-19 patients." (PMID 35505345, 2022). "The levels of plasma MPO-DNA and H3Cit were significantly higher in COVID-19 patients than healthy controls, and the level of plasma MPO-DNA positively correlated with the severity of COVID-19." (PMID 36224604, 2022). "The results showed that the plasma levels of extracellular dsDNA, NE, Histone–DNA, and MPO–DNA complexes were significantly increased in COVID-19 patients, particularly those with severe pneumonia (p < 0.01)." (PMID 35563204, 2022). "This group reported that levels of MPO/DNA complexes were increased in plasma of 32 patients with COVID-19 as compared to 21 healthy controls." (PMID 33982161, 2022). "They studied 33 patients with COVID-19 and 17 healthy donors and found that the amount of MPO/DNA complexes in plasma was significantly higher in COVID-19 patients as compared to healthy controls." (PMID 33982161, 2022). "Studies of patients with coronavirus disease 2019 (COVID-19) have shown that elevated levels of NET-specific markers (e.g., free DNA, MPO, and H3cit) are strongly associated with total neutrophil count." (PMID 35351657, 2022). "It has also been described that those levels of plasma MPO-DNA complexes increased in intubated and dead COVID-19 patients." (PMID 35154050, 2022). "Compared to healthy subjects, patients with COVID-19 have elevated serum levels of surrogate markers indicative of the existence of NETs, such as free-DNA, MPO-DNA complexes, and citrullinated histone H3." (PMID 36289900, 2022). "Indeed, we observed that neutrophils and monocytes derived from acute-phase COVID-19 patients showed a decreased capacity to kill intracellular bacteria, which was linked to a significant decrease in their ability to produce ROS and intracellular MPO (for neutrophils)." (PMID 35007290, 2022). "At the basal level, we observed a pronounced presence of MPO and H3Cit that enriched co-localization by neutrophils from COVID-19 patients." (PMID 36139764, 2022). "MPO-positive neutrophils were found in large numbers in both groups, but were twice as frequent in the sum score in the COVID-19 group compared to controls." (PMID 35237273, 2022). "The authors indicated that MPO-DNA complexes increased in COVID-19 and correlated directly with illness severity." (PMID 36093130, 2022). "Since, in our experiments, other immune cells were absent during infection of healthy neutrophils and we used a set number of cells compared to the neutrophilia seen during COVID-19, we observed a virus-mediated decrease in MPO and elastase release." (PMID 35203591, 2022). "Alongside other inflammatory markers, levels of MPO have been shown to increase in patients with COVID-19 compared to healthy controls." (PMID 35326373, 2022). "This has been evidenced by a recent study, where NETs were found to colocalized with platelets in pulmonary vasculature from COVID-19 autopsies and disease severity correlated directly with MPO-DNA complexes." (PMID 35409152, 2022). "Augmented NET release in COVID-19 neutrophils was sustained over time, with a trend toward increased production of NETs, as well as significantly elevated plasma cfDNA and MPO-DNA complexes on day 7 of illness." (PMID 34908534, 2022). "This study provides comparative, circulatory expression profiles of DEFA1, S100A8/A9 and MPO in COVID-19 patients with different clinical presentations." (PMID 34746027, 2021). "The observations of raised levels of these proteins much before the appearance of secondary infection provide important evidence for the association of higher expression levels of DEFA1/Calprotectin/MPO levels with COVID-19 severity." (PMID 34746027, 2021). "NET-remnants, such as citrullinated H3, circulating cell-free DNA, or MPO-DNA complexes have been found in abundance in the blood of COVID-19 patients." (PMID 34737734, 2021).
COVID-19 (continued). "In this study, circulating NETs were detected during the acute stage of the disease by the measurement of MPO-DNA complex assembly, which was significantly increased in severe COVID-19." (PMID 34228753, 2021). "The NET-remnants, including circulating cell-free DNA, citrullinated H3, or MPO-DNA complexes, are abundantly found in the circulation of patients with severe COVID-19." (PMID 34031543, 2021). "In COVID-19 patients with confirmed histone H3 presence on admission, the concentration of cfDNA, NE, MPO, and MPO-DNA complex was significantly increased compared to the histone H3 negative patients." (PMID 34568088, 2021). "We demonstrate that at ICU admission the levels of histone H3, MPO, and DNA-MPO complex were all significantly increased in COVID-19-positive patients compared to control samples." (PMID 34568088, 2021). "The level of histone H3 significantly correlated to MPO (rs = 0.440; p <0.001), and MPO-DNA complex (rs = 0.249; p = 0.009) in the COVID-19 patients." (PMID 34568088, 2021). "Autoantibodies recognizing type I IFN, DNA, proteinase-3, myeloperoxidase (MPO), phospholipids and prothrombin, have been observed in patients with COVID-19." (PMID 34685525, 2021). "This study revealed that an increased prevalence of MPO-DNA complexes in COVID-19 patients correlated directly with the severity of the disease." (PMID 34359859, 2021). "The markers for NETs formation, such as circulating DNA, neutrophil elastase (NE) activity, or myeloperoxidase-DNA complexes, were found in lung specimens of COVID-19 victims, as well as in sera and tracheal aspirates obtained from COVID-19 patients." (PMID 34445556, 2021). "Elevated levels of MPO in nasopharyngeal samples of COVID-19 patients were identified by proteomic analysis." (PMID 34746027, 2021). "Compared with controls, COVID-19 patients had higher levels of myeloperoxidase (MPO)–DNA complexes, both in serum and plasma." (PMID 34945111, 2021). "Patients with MIS-C displayed higher MPO levels than COVID-19 (96 ng/ml vs 40 ng/ml, respectively, p = 0.035)." (PMID 33841438, 2021). "Elevation of two indirect markers of NETosis, namely, cell-free DNA and MPO-DNA, in the plasma of patients with severe forms of COVID-19 has also been reported." (PMID 34840629, 2021). "Specific NET markers, like cell-free DNA, myeloperoxidase DNA (MPO-DNA), and citrullinated histone H3 (Cit-H3), are increased in sera from patients with COVID-19 compared to levels in uninfected controls." (PMID 33593982, 2021). "Taken together, these data suggest that COVID-19-associated metabolic abnormalities are at least partially dependent on the transcription factor REST and its downstream genes, which include MPO, apelin, and myostatin." (PMID 34916489, 2021). "Circulating markers of NET release — myeloperoxidase-DNA complexes and calprotectin — were assessed in 171 COVID-19 patients who had sufficient sera available for this analysis." (PMID 34166229, 2021). "ProNETosis gene signatures were observed in both pro- (MPO, ELA, and PRTN3) and pre-(PADI4) neutrophils and were associated with COVID-19 severity." (PMID 34616409, 2021). "Nasopharyngeal swabs of patients with COVID-19 are enriched in neutrophil myeloperoxidase, a highly abundant heme-containing protein responsible for coloration of mucus." (PMID 33888467, 2021). "In whole blood study, seven autoantigens were upregulated in blood of severe COVID-19 patients (MPO, PRTN3, PADI4, IFIH1, TRIM21, PTPRN2, and TSHR), while four autoantigens (MPO, PRTN3, IFIH1, and PADI4) were increased in blood of mild patients." (PMID 34276672, 2021). "When compared to HCs and patients with mild-to-moderate disease, significantly higher concentrations of MPO have been measured in blood samples acquired from severe COVID-19 patients." (PMID 34149717, 2021). "Defined as extracellular areas of DNA staining positive for MPO and CitH3, NETs have been detected in the airway, interstitial, alveolar and vascular compartments of COVID-19 lungs." (PMID 34149717, 2021).
COVID-19 (continued). "Sera from COVID-19 patients have been shown to have elevated levels of cell-free DNA, MPO/DNA complex, and citrullinated histone H3 (Cit-H3), which are NETosis specific markers." (PMID 34721760, 2021). "Blood levels of NETs were similar in controls and in SARS-CoV2 patients except for MPO+ CIt-H3+ NETs which were significantly higher in COVID-19 patients." (PMID 33708778, 2021). "We found that the plasma levels of complements C3 and MPO-DNA were positively related to coagulation indicator fibrin(-ogen) degradation products (C3: r = 0.300, p = 0.005; MPO-DNA: r = 0.316, p = 0.002) in COVID-19 patients." (PMID 33557911, 2021). "We recruited 135 COVID-19 patients and measured plasma levels of C5, C3, cell-free DNA and myeloperoxidase (MPO)-DNA." (PMID 33557911, 2021). "Zuo and colleagues demonstrated that COVID-19 patients present high serum levels of free DNA, myeloperoxidase-DNA (MPO-DNA) complexes, and citrunylated histone H3 (Cit-H3)." (PMID 33411735, 2021). "The experimental use of DNase-1-coated melanin-like nanospheres on plasma of COVID-19 patients resulted in significant reduction of NETs and MPO activity, as well as the decrease of the cytokines IL-1b, IL-6, and TNFα, involved in the NETs pathological loop." (PMID 34445556, 2021). "The levels of histone H3, MPO, and MPO-DNA complex were all significantly increased in COVID-19 patients on admission to the ICU as compared to both control groups." (PMID 34568088, 2021). "Studies of sera from patients (n = 50) with severe COVID-19 found elevated levels of specific markers of NETs such as cell-free DNA, myeloperoxidase-DNA, and histone H3." (PMID 34055688, 2021). "To define the frequency of ANCA autoimmunity in patients with SARS-CoV-2 infection we studied the serum ANCAs and the serum PR3 and MPO antigens in asymptomatic and in hospitalized COVID-19 patients at hospital admission and one week after the recovery." (PMID 34578298, 2021). "Another recent study found that markers of NET release (myeloperoxidase-DNA and citrullinated histone H3) in the sera of COVID-19 patients potently triggered NETosis in control neutrophils." (PMID 34737734, 2021). "Several studies have analyzed different typical markers of NETs release in COVID-19 patients, such as cell-free DNA (cfDNA), citrullinated histone 3 (citH3), MPO, NE, and complexes of these NETs components with DNA (for example MPO-DNA complexes)." (PMID 35052711, 2021). "The COVID-19 plasma was capable of activating neutrophils to form NETs and to release MPO-DNA in the media, which were significantly restrained by anti-C3a and anti-C5a neutralizing antibodies." (PMID 33557911, 2021). "In comparison with HDs, COVID-19 patients had significantly higher levels of NETs in the first week of admission quantified by measuring cell-free DNA (cfDNA) and myeloperoxidase (MPO)-DNA (all P < 0.001)." (PMID 33557911, 2021). "Overall, neutrophil infiltration through Neutrophilic plugs was detected in COVID-19 patients via Neutrophil Elastase (NE), Myeloperoxidase (MPO), and Citrullinated Histone H3 (citH3) staining." (PMID 34065210, 2021). "Elevated levels of soluble markers for NETs formation, such as circulating DNA, NE activity, or MPO-DNA complexes were found in sera from COVID-19 patients and they correlate with disease severity." (PMID 34445556, 2021). "MPO and TSHR were overexpressed in both lung autopsies and whole blood tissue and were associated with more severe COVID-19." (PMID 34276672, 2021). "Recently, two serum markers of neutrophil extracellular traps (NETs), myeloperoxidase (MPO)-DNA, and citrullinated histone H3 (Cit-H3) levels were found to be elevated in the serum of COVID-19 patients." (PMID 33013872, 2020). "Elevated serum NETs have been seen in COVID-19 patients (as indicated by elevations in cell-free DNA, MPO-DNA, and citrullinated histone H3 biomarkers)." (PMID 32646061, 2020).
COVID-19 (continued). "The pathogenic role of neutrophils in COVID-19 is likely due to the production of Neutrophil Extracellular Traps (NET), obtained with the release of DNA and MPO." (PMID 32825763, 2020). "Of interest, more recently, COVID-19 patients have been shown to have increased serum markers of NETs including myeloperoxidase-DNA (MPO-DNA) and H3Cit." (PMID 33202930, 2020). "Patients with COVID-19 have been found to have increased serum levels of myeloperoxidase–DNA complexes and citrullinated histone H3, both of which are markers of NETs." (PMID 33082228, 2020). "In our experiments, we show increased levels of serum myeloperoxidase and neutrophil elastase, likely due to enhanced degranulation of COVID-19 peripheral blood neutrophils." (PMID 33003471, 2020). "There’s currently no published evidence suggesting that MPO gene variants influence COVID-19 severity or outcomes." (PMID 41209585, 2025). "Elevated levels of NETs, myeloperoxidase (MPO), and neutrophils have been observed in the pulmonary vessels of patients with COVID-19, suggesting that targeting NETs may offer therapeutic potential." (PMID 41515964, 2025). "This study aimed to compare the levels of anti-PR3, anti-MPO, and anti-GBM autoantibodies in patients hospitalized with the Omicron variant of COVID-19 against those with the Delta variant, and to examine their correlations with clinical symptoms and laboratory parameters." (PMID 41239211, 2025). "MPO (OR [95% CI] = 0.99 [0.98, 1.00], p = 2.87 ×10-2, proportion = 8.7%) and APOF (OR [95% CI] = 0.98 [0.96, 1.00], p = 4.59 ×10-2, proportion = 15.7%) partially mediated the causal effect between LTL and COVID-19 hospitalization." (PMID 38882679, 2024). "Increases in NET markers such as histone-DNA, non-cleaved histone core protein 3 (H3) and MPO-DNA are linked to AKI development in COVID-19." (PMID 39340756, 2024). "MPO protein is upregulated early during COVID-19 as a critical indicator of neutrophil activity." (PMID 38882679, 2024). "This may offer a mechanistic reason for the sequestration of arginase-1 inside neutrophils in patients with severe COVID-19, although we also demonstrated that dexamethasone reduces neutrophil degranulation of both MPO and arginase-1 directly." (PMID 39253969, 2024). "The lack of correlations observed between some markers considered specific, such as CitH3 with MPO-DNA and NE-DNA, has been reported in COVID-19 between CitH3 and MPO-DNA, and between CitH4-DNA and NE-DNA, which showed opposite trends in COVID-19 severity assessment." (PMID 38243237, 2024). "In addition, MPO was found to be relevant to the COVID-19 pandemic in the past three years; therefore, the most recent information on the role of MPO in COVID-19 has also been included and discussed in detail in this review." (PMID 38275657, 2024). "However, some researchers view MPO’s role in COVID-19 differently, emphasizing its antibacterial action." (PMID 38275657, 2024). "Corticosteroid treatment in critical cases of COVID-19 is associated with a lower incidence of AKI and reduced NET formation, as indicated by attenuated plasma concentrations of extracellular histones and MPO-DNA." (PMID 39340756, 2024). "Finally, six plasma proteins were found to mediate the causal effect between LTL and COVID-19 outcomes, such as BDNF, QPCT, FAS, MPO, SFTPB, and APOF." (PMID 38882679, 2024). "The symptoms caused by COVID-19 are related to the cytokine storm that it triggers: the excessive immune response leads to the excessive activation of neutrophils and the subsequent production of large amounts of MPO, resulting in the series of clinical manifestations of COVID-19." (PMID 38275657, 2024). "Furthermore, six proteins partially mediated the causality of LTL on COVID-19 outcomes, including BNDF, QPCT, FAS, MPO, SFTPB, and APOF." (PMID 38882679, 2024). "For example, MPO has been found to be upregulated in patients with COVID-19." (PMID 38882332, 2024).
COVID-19 (continued). "This review provides a comprehensive analysis of the diverse roles of MPO in the progression of several diseases, including cardiovascular diseases (CVDs), neurodegenerative diseases, cancers, renal diseases, and lung diseases (including COVID-19)." (PMID 38275657, 2024). "Also, another clinical trial focusing on COVID-19-positive patients found that plasma MPO levels in patients were significantly higher than those in healthy controls." (PMID 38275657, 2024). "This, and the high MPO-DNA and NE-DNA correlations in the 3 levels of severity and during the entire evolution, offer little doubt as to the existence of NETosis in hospitalised patients with COVID-19, including in less severe patients." (PMID 38243237, 2024). "Clinical research on COVID-19 found that levels of MPO were significantly upregulated in the serum of COVID-19 patients compared with healthy individuals, and serum MPO levels in the recovered population were reduced to levels comparable to those in healthy people." (PMID 38275657, 2024). "Moreover, an increase in serum MPO in COVID-19 patients was observed, followed by a decrease to a normal level in recovering patients." (PMID 37283736, 2023). "Neutrophil MPO may increase EG shedding in COVID-19, and inhibiting MPO activity may protect against EG degradation." (PMID 37147421, 2023). "The MPO concentration is significantly elevated in COVID-19 patients who were admitted to a hospital intensive care unit (ICU) and is associated with mortality and poor prognosis in COVID-19." (PMID 37908356, 2023). "These investigations documented that plasma MPO-DNA complexes were found to be elevated in COVID-19 patients and correlated with disease severity, as evidenced by a higher sequential organ failure assessment (SOFA) score, incidence of intubation and death, and lower PaO2/FiO2 ratios." (PMID 37828990, 2023). "Interestingly, elevated NETs components, including citrullinated histones, cell-free DNA, and myeloperoxidase (MPO)-DNA complexes, have also been observed in COVID-19 patients." (PMID 37533131, 2023). "Furthermore, a high positive correlation between lipid peroxidation and MPO intensity was observed in lung tissues of COVID-19 patients." (PMID 36768969, 2023). "NE and MPO levels were higher in the serum of COVID-19 patients." (PMID 36902466, 2023). "The MPO concentration could reach very high values (>100 ng/mL) similar to those observed in COVID-19 patients during their stay in the ICU." (PMID 37238982, 2023). "The levels of cf-DNA, MPO-DNA, and CitH3 are elevated in the serum of COVID-19 patients." (PMID 38283037, 2023). "Additionally, we report that in the lungs of post-mortem COVID-19 patients, MPO positively correlates with oxidized DNA and lipid peroxidation." (PMID 36768969, 2023). "eDNA, MPO-DNA, and CitH3 showed significant increases in sera from COVID-19 patients." (PMID 36902466, 2023). "DDS inhibits neutrophil myeloperoxidase, inflammation, and neutrophil chemotaxis, as well as the expression of inflammatory signaling pathways and the generation of reactive oxygen species (ROS), known complications of COVID-19." (PMID 37764145, 2023). "In each of these examples, neutrophils were detected and frequently demonstrated strong neutrophil elastase (NE) activity, and myeloperoxidase (MPO) expression (a common neutrophil marker) is frequently observed around centers of SARS-CoV-2 infection in postmortem COVID-19 tissues." (PMID 37006263, 2023). "Indeed, a recent study identified exuberated NETs in broncho-alveolar lavage and lung tissue identified as cell-free DNA, MPO-DNA complex in COVID-19 patients." (PMID 35053307, 2022). "Indeed, NET components such as MPO-DNA complexes are markers of disease severity in patients suffering from COVID-19." (PMID 35741047, 2022). "Furthermore, MPO-positive neutrophils were found in significantly higher numbers in lungs and kidneys of COVID-19 patients and correlated with local MASP-2 deposition." (PMID 35237273, 2022).